ACSL1 (acyl-CoA synthetase long chain family member 1)
Diseases named in the same sentence as ACSL1 in open-access papers (continued):
Sharing a sentence is not in itself a finding about the gene and the disease.
triple-negative breast carcinoma (2 papers, 2024 to 2025). An invasive breast carcinoma which is negative for expression of estrogen receptor (ER), progesterone receptor (PR), and human epidermal growth factor receptor 2 (HER2). "Furthermore, in the triple-negative breast cancer cell line BT549, long-chain acyl-CoA synthetase 1(ACSL1) mediates the synthesis of α-tocopherol succinate (αESA, a representative polyunsaturated fatty acid) and induces ferroptosis in BT549 cells, which cannot be suppressed by GPX4 interference." (PMID 39664391, 2024).
ulcerative colitis (2 papers, 2022 to 2025). An inflammatory bowel disease involving the mucosal surface of the large intestine and rectum. "Our findings indicated that DPP10, MST1L, DPP10‐AS1, CEP55, ACSL1, MGP, OLFM4, and SGK1 may act as diagnostic biomarkers for ulcerative colitis and that differential immune infiltration cells may help to illustrate the progression of ulcerative colitis." (PMID 34939750, 2022). "To further validate these biomarkers' expression in ulcerative colitis, we determined mRNA levels of SGK1, CEP55, ACSL1, OLFM4, and DPP10 in lipopolysaccharides (LPS)‐stimulated Raw264.7 cells by quantitative reverse transcription‐polymerase chain reaction." (PMID 34939750, 2022). "To further validate the expression of these candidate biomarkers in ulcerative colitis, we determined mRNA levels of SGK1, CEP55, ACSL1, OLFM4, and DPP10 in LPS‐stimulated Raw264.7 cells by qPCR in in vitro bioassays." (PMID 34939750, 2022). "Compared with the normal group, the expression of SGK1, CEP55, ACSL1, OLFM4, and MGP was markedly increased in the DSS‐induced ulcerative colitis group." (PMID 34939750, 2022).
viral infection (2 papers, 2023). "ACSL1 may be possibly a novel therapeutic target to limit inflammation in COVID-19 or other viral infections." (PMID 38075884, 2023). "ACSL1 and ACSL4 inhibitions prevent ferroptosis during viral infections, thereby protecting the host." (PMID 38075884, 2023).
adenomyosis (1 paper, 2025). The growth of endometrial tissue inside the muscular wall of the uterine corpus. "Genes that promote ferroptosis, such as ACSL1, ALOX15, STEAP3, and SLC11A2, were upregulated in adenomyosis." (PMID 40911580, 2025).
Age-related cataract (1 paper, 2021). A type of cataract (opacification of the lens) that forms during the course of aging. "We found that variants in the genes associated with age-related cataracts, including NAALADL2 and ACSL1, functioned in the metabolism pathway." (PMID 34299682, 2021). "Some of these genes associated with age-related cataracts include FRMD4B, NAALADL2, LOC105377670, LINC00968, LOC101929415, CTNNA3, LOC107984170, PRCP, and ZNF423, whereas others with a reduced risk include CFAP74, ACSL1, LOC101927668, LOC105369844." (PMID 34299682, 2021).
Azoospermia (1 paper, 2025). Absence of any measurable level of sperm,whereby spermatozoa cannot be observed even after centrifugation of the semen pellet. "Notably, dysregulation of fatty acid synthesis and activation pathways has been observed in Sertoli cells of patients with non-obstructive azoospermia, accompanied by significantly reduced ACSL1 expression, underscoring the importance of lipid metabolic homeostasis in male reproduction." (PMID 41375492, 2025).
cardiomyopathy (1 paper, 2021). A disease of the heart muscle or myocardium proper. "The critical role of lipotoxicity in cardiomyopathy is supported by the observation that ACSL-1 was upregulated in the heart of obese animals suggesting propagation of cardiac lipid accumulation." (PMID 33716957, 2021).
cell renal cell carcinoma (1 paper, 2025). "In cell renal cell carcinoma, the subgroup characterized by elevated ACSL1 expression showed enrichment in pathways associated with fatty acid metabolism and demonstrated heightened expression of genes linked to ferroptosis." (PMID 40337509, 2025).
cerebrovascular diseases (1 paper, 2025). "While numerous studies have investigated targeting ACSL4 to mitigate brain injury in cerebrovascular disease, the roles of ACSL1 and ACSL3 as key regulators of ferroptosis remain underexplored." (PMID 41288931, 2025). "The ACSL family consists of five isoforms—ACSL1, ACSL3, ACSL4, ACSL5, and ACSL6—each of which has been implicated in the pathogenesis, treatment, and prognosis of diverse conditions, including metabolic disorders, cancers, cardiovascular and cerebrovascular diseases, and other clinical conditions." (PMID 41288931, 2025).
Chagas disease (1 paper, 2024). A parasitic infection caused by Trypanosoma cruzi. "On the other hand, our study is the first that correlates the increase in ACSL1 with Chagas disease." (PMID 39000601, 2024).
cognitive deficits (1 paper, 2026). "Our study unveils ACSL1-mediated lipoimmunity reprogramming of microglia as a core mechanism underlying cognitive impairment in AUD and proposes a novel targeted therapeutic strategy." (PMID 41645661, 2026). "We further developed a dual-targeted lipid nanoparticle system for microglia-specific ACSL1 silencing, which effectively ameliorated ethanol-induced cognitive deficits in mice." (PMID 41645661, 2026).
colon adenocarcinoma (1 paper, 2010). "Moreover, in colon adenocarcinoma where ACSL4 expression is associated with an increased proliferation rate, ACSL1 expression was not changed or was even down-regulated." (PMID 21085606, 2010).
endometrial cancer (1 paper, 2024). Primary or metastatic malignant neoplasm involving the endometrium (mucous membrane that lines the endometrial cavity). "Moreover, the data from The Human Protein Atlas indicate that ACSL1, ACSL4, and ACSL5 are favorable prognostic markers in renal cancer, urothelial cancer, and endometrial cancer." (PMID 38539505, 2024).
HCMV infection (1 paper, 2013). "To confirm the transcript results, we analyzed the protein levels of two of the siRNA hits, ACSL1 and ELOVL3, during HCMV infection and found that both proteins were elevated." (PMID 23696731, 2013).
heart failure (1 paper, 2022). Inability of the heart to pump blood at an adequate rate to meet tissue metabolic requirements. "In addition, since ACSL1 expression is low in heart failure when ACSL1 is forcibly expressed to enhance the acylation of long-chain FAs, mitochondrial energy production is maintained, resulting in cardioprotection in pressure overload-induced heart failure." (PMID 35323653, 2022).
hypothyroidism (1 paper, 2021). Abnormally low levels of thyroid hormone. "In our study, the expression of Fasn, Acsl1, Acsl5, Ehhadh, and Acox1 were significantly down-regulated in hypothyroidism rats, indicating that the synthesis of fatty acid and the oxidation process of fatty acids were inhibited." (PMID 33959028, 2021). "These DEPs including Pygl, Pklr, Pc, Ehhadh, Acox1, Fasn, Acly, Acsl1, Acsl5, Pgm1, Suclg1, Gpt, Idh1, Fh, and Adh1 maight be as target proteins of AMR and its fractions for hypothyroidism." (PMID 33959028, 2021).
Immunodeficiency (1 paper, 2023). Failure of the immune system to protect the body adequately from infection, due to the absence or insufficiency of some component process or substance. "ACSL1 was linked to the intestinal immune network for IgA production, immunodeficiency, ribosome, along with splicesome." (PMID 37928394, 2023).
inflammatory bowel disease (1 paper, 2020). A spectrum of small and large bowel inflammatory diseases of unknown etiology. "Previous reports associated patients with inflammatory bowel disease (IBD) with the over-expression of ACSL1 and ACSL5 in the terminal ileum and colon." (PMID 33050166, 2020).
knee osteoarthritis (1 paper, 2025). "Notably, ACSL1, which is related with PPAR signaling pathway has been demonstrated to be closely associated with knee osteoarthritis and NLRP3." (PMID 40790756, 2025).
leukemia (1 paper, 2016). A malignant (clonal) hematologic disorder, involving hematopoietic stem cells and characterized by the presence of primitive or atypical myeloid or lymphoid cells in the bone marrow and the blood. "In addition, there was a lower expression level of ACSL1 in brain, cervical, esophageal, head and neck, leukemia, liver, and sarcoma cancers." (PMID 27171439, 2016).
lung diseases (1 paper, 2023). "Statistical analyses demonstrated that mRNA expression of ACSL1, ACSL3 and ACSL4 in lung and airway epithelial cells among lung diseases." (PMID 36639836, 2023).
lymphoma (1 paper, 2022). A malignant (clonal) proliferation of B- lymphocytes or T- lymphocytes which involves the lymph nodes, bone marrow and/or extranodal sites. "Similar to CPT1a inhibition, palmitate-induced energy production by CD37KO lymphoma cells was significantly diminished upon treatment with ACSL1 inhibitor compared to WT control cells." (PMID 36100608, 2022).
myocarditis (1 paper, 2022). Myocarditis is a condition that is characterized by inflammation of the heart muscle (myocardium). "Also, we confirmed not only PDK4, but also CPT1A and ACSL1, which are known to be key regulators of fatty acid metabolism, are the target transcripts of CEBPB in classical monocytes in BNT162b2-myocarditis." (PMID 36225942, 2022).
non-alcoholic steatohepatitis (1 paper, 2020). "However, in a transgenic murine PTEN knockout, non-alcoholic steatohepatitis (NASH)-induced model for HCC, a quantitative proteomic study found that ACSL1 protein levels were fractionally decreased and ACSL5 levels reciprocally up-regulated." (PMID 32286604, 2020).
pancreatic ductal adenocarcinoma (1 paper, 2024). An infiltrating adenocarcinoma that arises from the epithelial cells of the pancreas. "Another recent study demonstrated that PPAR signal can promote ferroptosis by upregulating the expression of ACSL1/4 in pancreatic ductal adenocarcinoma." (PMID 39735727, 2024).
periodontitis (1 paper, 2025). An acute or chronic inflammatory process that affects the tissues that surround and support the teeth. "Likewise, methotrexate-loaded EVs derived from human umbilical cord mesenchymal stem cells suppressed proinflammatory macrophage activation through acyl-CoA synthetase-1 (ACSL1) downregulation and OXPHOS restoration, ultimately improving therapeutic outcomes in periodontitis." (PMID 41153802, 2025).
Rb (1 paper, 2022). "Advanced Rb subjects showed a significantly high degree of expression for fatty acid metabolism genes such as MYCLD and ACSL1, compared to non-advanced Rb tumors." (PMID 35626705, 2022).
skin tumors (1 paper, 2019). "When its expression is combined with other DNFA genes in PCA, ACSL1 expression strongly correlates with PC1 towards healthy tissues and results in better separation of skin tumors from healthy skin tissues." (PMID 31316083, 2019).
systemic lupus erythematosus (1 paper, 2025). An autoimmune multi-organ disease typically associated with vasculopathy and autoantibody production. "Our results show that IFN-I induces ACSL1 in macrophages via its interferon-α/β receptor, and consequently that expression of ACSL1 is increased in myeloid cells from individuals with systemic lupus erythematosus (SLE), an autoimmune condition characterized by increased IFN production." (PMID 39675509, 2025).
Zinc deficiency (1 paper, 2013). A deficiency of the essential metal Zinc; an essential cofactor for many enzymes. "In accordance, hepatic expression of Acsl1 (acetyl-CoA synthetase long-chain family member 1), a gene responsible for fatty acid activation was down-regulated only by dietary zinc deficiency." (PMID 24155903, 2013). "As expected, zinc deficiency alone increased hepatic triglyceride, cholesterol and FFA levels in association with down-regulation of PPAR-α and lipid metabolism genes including Acsl1, Acox1 and Apob." (PMID 24155903, 2013).
tumor (52 papers, 2015 to 2025). "In primary lung tumors, a higher expression of ACSL1 was significantly associated with a low tumor grade in lung ADC, suggesting that ACSL1 is involved in the differentiation of lung ADC." (PMID 38539505, 2024). "The study linked this increased tumor load to a gradual downregulation of two metabolic genes, Acyl-CoA synthetase long chain family member 1 (Acsl1) and aldehyde dehydrogenase family member 2 (Aldh2) mediated through a specific miRNA, miR-27a-3p." (PMID 38681863, 2024). "In summary, the present study demonstrated that ACSL1 plays a crucial role in the regulation of TNFα mediated excessive production of GM-CSF associated with the inflammatory process that is involved in tumor growth." (PMID 31581558, 2019). "The molecular mechanisms by which rs8086 ACSL1 polymorphism affects tumor behavior and recurrence are under investigation." (PMID 27992526, 2016). "Similarly, in oncology, semaglutide reprograms tumor-associated macrophages via the GLP-1R/PPARG/ACSL1 pathway, promoting M1 polarization and suppressing tumor progression." (PMID 41226200, 2025). "Functional assays with ACSL1-overexpressing ccRCC cells and a xenograft mouse model evaluated its impact on tumor behavior." (PMID 41054261, 2025). "Low ACSL1 expression has been related with adverse tumor histopathology and reduced overall survival in patients with ccRCC, suggesting its potential as a prognostic marker." (PMID 41288931, 2025). "Collectively, dysregulated expression of ACSL1, ACSL4 and ACSL5 isoforms in CRC tissues is associated with tumour progression and patient outcomes, warranting additional research for biomarker development." (PMID 41154605, 2025). "We detected marked differences in the immunohistochemical staining of two key proteins, ACSF2 and ACSL1, between tumor tissue samples and normal tissue samples." (PMID 39524444, 2024). "Within the 8 Mitochondrial-Related Genes (MRGs) analyzed, ACSL1, MTHFD2, and MRPL13 were notably overexpressed in both the high-risk group and tumor tissues." (PMID 38310106, 2024). "To provide further evidence of the accuracy of our observations, we performed Western Blot and uncovered that the protein expression of ACSL1 was almost entirely lower in ccRCC tumorous tissues versus adjacent normal tissues." (PMID 37608295, 2023). "At the same time, we evaluated the predictive role of ACSL1 expression on the prognosis of ccRCC using ROC curves and observed that ACSL1 was highly accurate in predicting the outcome of normal and tumor samples." (PMID 37608295, 2023). "We then explored the differential DNA methylation levels of ACSL1 between tumor and normal tissues, discovering that the aggerated methylation for all the probes in ACSL1 gene loci was more pronounced in tumor tissues versus normal tissues." (PMID 37608295, 2023). "Taken together, our findings point to ACSL1 as a biomarker for prognostic prediction of ccRCC, identifying the tumor microenvironment (TME) phenotype, and even contributing to treatment decision-making in ccRCC patients." (PMID 37608295, 2023). "The protein expression of ACSL1 was markedly less in tumor tissues versus the corresponding normal samples." (PMID 37608295, 2023). "We also examined the mRNA expression levels of ACSL1 in the four groups of tumor tissues by Realtime PCR." (PMID 36661650, 2022). "ACSL1 has a marked preference for oleate and linoleate, and can promote ungoverned cell growth, facilitate tumor invasion and evade programmed cell death." (PMID 36507355, 2022).
tumor (continued). "It was found that OIP5 silencing in nude-mouse tumor tissues not only slowed tumor growth and reduced size, but also significantly downregulated the expression of fatty acid pathway-related genes (ACSL1, ACSL2, and HADH)." (PMID 36661650, 2022). "ACSL1 has been reported to play a crucial role in the regulation inflammatory process that is involved in tumor growth and metastasis in BRCA by regulating lipid metabolism and patients." (PMID 35739271, 2022). "FATP4, CD36, and ACSL1 expression in NMIBC tumor tissues revealed a weak positive correlation among them (FATP4 vs. CD36, Spearman rho = 0.273, p < 0.001; FATP4 vs. ACSL1, Spearman rho = 0.378, p < 0.001; CD36 vs. ACSL1, Spearman rho = 0.260, p < 0.001)." (PMID 34257543, 2021). "Down-regulated genes contain markers enriched in mature hepatocytes (Tat, Cyp7a1, Apoa5, Pck1, Cyp3a11, Mup3 or Acsl1) and tumor suppressors (Lect2, Wfdc17 or Efemp1)." (PMID 32372053, 2020). "Clinically, high FATP4 in tumor cells was associated with female gender (p = 0.05), high TNM stage (p = 0.039), tumor necrosis (p = 0.009), and tumor recurrence (p = 0.037), while high ACSL1 was only related to female gender (p = 0.023)." (PMID 31089396, 2019). "This study showed that membranous expression of CD36 and FATP4 was higher in RCC tumor tissues than in normal tissues, whereas cytoplasmic ACSL1 was reduced in RCC tumor cells." (PMID 31089396, 2019). "In this study, we evaluated the differential immunohistochemical expression of fatty acid transporters including CD36, FATP4, and ACSL1 between RCC tumor cells and normal renal tubular epithelial cells." (PMID 31089396, 2019). "While ACSL1 mRNA was frequently reported to be downregulated in multiple human malignancies, the oncogenic or tumor-suppressive function of ACSL1 differed considerably across cancer types." (PMID 31089396, 2019). "Thus, we have identified a “risk genotype” of ACSL1 gene that confers constitutive high levels of the enzyme, which is involved in the activation of fatty acids through conversion to acyl-CoA and has been recently related to increased invasiveness of tumor cells." (PMID 27992526, 2016). "Overexpression of ACSL1 and ACSL4 has been linked to enhanced tumour aggressiveness." (PMID 41154605, 2025). "ACSL1 mediates ferroptosis and inhibits tumor growth in TNBC." (PMID 39524444, 2024). "ACSL1 specifically was reported to be associated with a shorter survival time in GBM patients, and ACSL1 inhibitors could reduce GBM tumor growth both in vivo and in vitro." (PMID 38609948, 2024). "However, in MDA-231 cells, ACSL1 plays a crucial role in regulating the excessive production of TNFα-mediated inflammatory processes related to tumor growth." (PMID 39524444, 2024). "As a result, ACSL1 was mediumly expressed in the membrane and cytoplasm of cells in renal tubules with moderate intensity at a rate of 75%-25%, but it was barely detectable in ccRCC tumor cells." (PMID 37608295, 2023). "Additionally, the IHC staining of the tumor sections showed the tumors from the combination therapy group had the lowest expression levels of ACSL1, STAT3, p-STAT3, and Ki-67." (PMID 35574370, 2022). "ACSL1 has also been reported to play a crucial role in the regulation of GMCSF production, which is associated with the inflammatory process that is involved in tumor growth." (PMID 35739271, 2022). "DCA also increased ACSL1 expression in vivo in AML tumor cells engrafted in NSG mice." (PMID 35563698, 2022). "However, ACSL1 was proposed to function as either an oncogene or tumor-suppressive gene depending on the cancer type." (PMID 34257543, 2021). "The ACSL1 encoded protein, involved in fatty acid metabolism, was positive in tumor cells from TPIT tumors and only very weak or negative in tumors of the PIT1 and SF1 lineage." (PMID 34758873, 2021).